GPX4 (glutathione peroxidase 4)
Diseases named in the same sentence as GPX4 in open-access papers (continued):
Sharing a sentence is not in itself a finding about the gene and the disease.
colorectal cancer (continued). "The regulation of GPX4 in colorectal cancer is mostly dependent on ferroptosis." (PMID 40969276, 2025). "Therefore, in this scenario, TIMP1-induced activation of the PI3K/Akt pathway and subsequent upregulation of GPX4 contribute to resistance against sorafenib-triggered ferroptosis in colorectal cancer cells." (PMID 38562143, 2024). "Similarly, several studies show that disrupting PI3K/Akt pathway activity in colorectal cancer enhances treatment efficacy with GPX4 inhibitors like RSL3 plus sorafenib." (PMID 38562143, 2024). "Furthermore, AKT, FTO and GPX4 were expressed at greater levels in cancer than adjacent tissues and found FTO and GPX4 are potential biomarkers in colorectal cancer." (PMID 38102129, 2023). "However, in colorectal cancer cells, GPX4 can be negatively regulated by acyl-coenzyme A dehydrogenase, short/branched chain (ACADSB)." (PMID 37488128, 2023). "RSL3 drives ferroptosis through GPX4 inactivation and ROS production in colorectal cancer." (PMID 37238692, 2023). "The depletion of SFRS9 represses colorectal cancer progression by enhancing ferroptosis by GPX4." (PMID 35847361, 2022). "Glutathione peroxidase 4 inhibition combined with chemotherapy or targeted therapy may be a promising therapy for colorectal cancer." (PMID 35719967, 2022). "Over-expression of GPX4 prevented ferroptosis in colorectal cancer in in vitro studies." (PMID 33121039, 2020). "This study demonstrated that UA could effectively inhibit CRC proliferation by inducing ferroptosis via regulation of system xc- subunits and miR-214-3p/Stat3/GPX4 axis, suggesting UA could serve as a promising anti-colorectal cancer candidate requiring further validation and optimization." (PMID 41341590, 2025). "Thus, it is worth to verify experimentally whether the IFNγ/IFNGR2/APC/TCF4/GPX4 axis exists in colorectal cancer cells that, once taking on actions, triggers ferroptosis in colorectal CSCs." (PMID 37671945, 2023). "In pancreatic ductal adenocarcinoma (PDAC) and colorectal cancer (CRC), GRP78 suppresses ferroptosis by interacting with and stabilizing glutathione peroxidase 4 (GPX4), an enzyme critical for inhibiting lipid peroxidation." (PMID 40002794, 2025). "It has the potential to induce ferroptosis in colorectal cancer and hepatocellular carcinoma by elevating the levels of ROS and SOD, while downregulating GPX4, GSH, and IGF2BP3." (PMID 41465430, 2025). "Baicalein induces ferroptosis in colorectal cancer cells by the janus kinase 2 (JAK2)/ signal transducer and activator of transcription 3 (STAT3)/ glutathione peroxidase 4 (GPX4) pathway." (PMID 41460836, 2025). "Macrophage-specific expression of GPX4 decreased in both human COAD and READ compared to the corresponding normal tissues (p < 0.001 and 0.01 for COAD and READ, respectively), suggesting that decreased expression of GSTA4 may be associated with macrophage ferroptosis in human colorectal cancer." (PMID 39819335, 2025). "Studies have shown that the knockdown or pharmacological inhibition of USP8 increases the sensitivity of colorectal cancer cells to ferroptosis and that USP8 interacts with GPX4 and prevents GPX4 protein degradation by affecting GPX4 deubiquitination." (PMID 40136465, 2025). "To confirm this metabolic phenomenon in cancer patients, we obtained cancerous and paracancerous tissue samples from 23 pairs of colorectal cancer patients and examined GLS1 and GPX4 expression through immunohistochemistry." (PMID 40259435, 2025). "Apatinib reduces the expression of GPX4 and upregulates the expression of ACSL4 and ECOVL6 to promote ferroptosis in colorectal cancer cells." (PMID 40721409, 2025).
colorectal cancer (continued). "Here, we found that CDH17 and GUCY2C are co-overexpressed in colorectal cancer cells and developed a bispecific antibody-drug conjugate (BsADC) targeting CDH17 and GUCY2C, conjugated with the ferroptosis inducer RSL3 (a GPX4 inhibitor)." (PMID 40721409, 2025). "In one study, 3,5-di-CQA was shown to suppress mitochondrial dysfunction and ferroptosis by regulating the expression of GPX4, ACSL4, and SLC7A11 in colorectal cancer cells." (PMID 39754271, 2025). "In particular, 3,5-di-caffeoylquinic acid, a MO component, suppresses mitochondrial dysfunction and ferroptosis by regulating the expression of GPX4, ACSL4, and xCT in colorectal cancer cells." (PMID 40365315, 2025). "FOXA2 suppression by TRIM36 was found to exert an anti-cancer function in colorectal cancer (CRC) by promoting NRF2/GPX4-mediated ferroptosis, emphasizing the potential of targeting the Nrf2/GPX4 pathway for therapeutic interventions in cancer." (PMID 39036600, 2024). "By generating ferroptosis and lowering the level of GPX4 expression in CRC cells, our findings provided further confirmation that ferroptosis can be an effective treatment for colorectal cancer." (PMID 39031216, 2024). "So far, GPX4 and SLC7A11 remain the principal targets for ferroptosis development in colorectal cancer." (PMID 39031216, 2024). "Studies have demonstrated that in MC38 colorectal cancer and B16F10 melanoma models, specific deletion of GPX4 in Tregs leads to significant accumulation of lipid peroxides (LPOs), inducing ferroptosis upon TCR/CD28 co-stimulation and impairing Treg function." (PMID 39850905, 2024). "Cisplatin leads to GSH depletion and GPx4 inactivation, inducing both ferroptosis and apoptosis in A549 non-small-cell lung cancer (NSCLC) cells and colorectal carcinoma (HCT116 CRC) cells." (PMID 39125992, 2024). "Accordingly, the overexpression of GPX4 was described in EGFR-TKI-resistant lung adenocarcinoma and colorectal cancers." (PMID 36899869, 2023). "We examined the impact of GPX4 gene knock-out, using the CRISPR/Cas-9 technique, on ferroptosis induction in the HCT116 colorectal cancer cell line." (PMID 38139836, 2023). "Moreover, our preliminary immunohistochemical staining showed that the expression intensity of both ACSL4 and GPX4 was higher in colorectal cancer tissues than in paracancerous tissues, which also suggested that ferroptosis might have a regulatory role in colorectal cancer." (PMID 37207153, 2023). "In colorectal cancer cells, RSL-3 induced the onset of ferroptosis by prompting GPX4 inactivation, thereby reducing the proliferative capacity of tumor cells." (PMID 37207153, 2023). "Mechanistic studies showed that GPX4 expression and ferrous iron were increased in 5-FU and AZ628-derived CRC persister cells, residual subcutaneous transplantation tumors, and colorectal cancer patients undergoing neoadjuvant chemoradiotherapy." (PMID 35719967, 2022). "Studies have proved that HSPA5 can bind to GPX4 and inhibit GPX4 protein degradation, thereby inhibiting ferroptosis in pancreatic ductal adenocarcinoma (PDAC) cells and colorectal cancer (CRC) cells." (PMID 36591279, 2022). "Macrophages phagocytose tumor cells, and these eight key enzymes were identified in combination with GPX4, a critical protein of ferroptosis, suggesting that the change in the expression of these eight key enzymes in TAMs may be involved in the regulation of colorectal cancer through cell death." (PMID 36552870, 2022). "As expected, the results indicated that most of these eight amino acid-metabolizing enzymes in TAMs, except for GPX4 and HMGSC1, have a significant effect on the development and progression of colorectal cancer." (PMID 36552870, 2022). "In KRAS-mutant colorectal cancer cells, inhibition of the Nrf2/HO-1 axis contributed to the promotion of ferroptosis induced by RSL3, a GPX4 inhibitor." (PMID 35350242, 2022).
colorectal cancer (continued). "So far, we have demonstrated that GPX4 and FTH1 are upregulated in anti-colorectal cancer drug-tolerant persister cells and tumors." (PMID 35719967, 2022). "It is found that miR-15a-3p participates in the ferroptosis process of colorectal cancer, can directly bind to the 3′-UTR of GPX4 and inhibit its activity, resulting in the increase of intracellular ROS, intracellular Fe2+ level and MDA." (PMID 36408273, 2022). "After exploring the mechanism, it was found that miR-539 can regulate the expression of TIP and indirectly down regulate the expression of GPX4 by activating SAPK/JNK pathway, promoting the process of ferroptosis and inhibiting colorectal cancer cells." (PMID 36408273, 2022). "Next, we detected the GPX4 and FTH1 levels in colorectal cancer patients undergoing neoadjuvant chemoradiotherapy by immunohistochemistry, and found both protein levels were up-regulated, compared with the patients without neoadjuvant chemoradiotherapy." (PMID 35719967, 2022). "RBF also can inhibit the growth and metastasis of colorectal cancer by triggering RIP3-dependent necrotizing ptosis and inducing glutathione peroxidase 4 (Gpx4) inactivation to induce oxidative stress." (PMID 33995111, 2021). "Additionally, FTO knockout decreases glutathione peroxidase 4 (GPX4) expression in colorectal cancer (CRC) cells, promoting ferroptosis by modulating m6A modification at the 193rd site of GPX4 mRNA." (PMID 40001550, 2025). "Combining iron chelation with other ferroptosis-modulating approaches, such as GPX4 inhibition, may enhance therapeutic precision and address the multifactorial nature of diseases like NASH and colorectal cancer." (PMID 40565780, 2025). "In mouse models of melanoma and colorectal cancer, I3A administration significantly reduced the antitumor efficacy of the ferroptosis inducer RSL3, accompanied by reduced lipid peroxidation and preserved glutathione peroxidase 4 levels." (PMID 41354345, 2025). "Colorectal cancer exhibits oxaliplatin resistance mediated by Fusobacterium nucleatum via the E-cadherin/β-catenin/TCF4/GPX4 axis, and the KIF20A/NUAK1/PP1β/GPX4 pathway may further support this resistance." (PMID 39935430, 2025). "A negative correlation between relative GPX4 overexpression and lipid peroxidation markers has been observed in diffuse large B-cell lymphoma, lung squamous cell carcinoma, and colorectal cancer." (PMID 39723384, 2024). "Except for GPX4 and HMGCS1, the results were consistent with the expression levels in cancer tissues and normal colorectal tissues, as the expression levels decreased with the deterioration of clinicopathological conditions in patients with colorectal cancer." (PMID 36552870, 2022). "TCGA and GTEx data revealed high GPX4 and SLC7A11 expression in colorectal cancer." (PMID 35978266, 2022). "Unexpectedly, the expression of GPX4 and HMGCS1 in colorectal cancer was upregulated." (PMID 36552870, 2022). "Additionally, grape-derived exosome-like nanovesicles can deliver natural polyphenols, downregulate GPX4, upregulate transferrin receptor 1 (TFR1), and enhance iron uptake, leading to excessive ROS accumulation and ferroptosis, effectively inhibiting colorectal cancer cell proliferation." (PMID 40642010, 2025). "These include the induction of ferroptosis in gallbladder cancer via downregulation of GPX4 through the p62-Keap1-Nrf2-HMOX1 axis, as well as the promotion of Bax/Bcl-2 alterations, activation of caspases, and induction of G2/M phase arrest through mitochondrial pathways in colorectal cancer models." (PMID 40978472, 2025).
colorectal cancer (continued). "In our sensitive HCT116 WT and GPX4 KO mutated cell lines, the lack of PROM2 expression at the mRNA level may result from the sensitivity of colorectal cancer cell lines to ferroptotic cell death, similar to previously reported findings." (PMID 38139836, 2023). "Therefore, we used the correlation of the expression level of genes with the prognosis of colorectal cancer patients as an evaluation index, and finally identified eight critical enzymes of amino acid metabolism in colon TAMs, namely, ACADM, ACADS, GPX4, GSR, HADH, HMGCL, HMGCS1 and IDH1." (PMID 36552870, 2022). "In colorectal cancer cells, CTX neither affected proliferation or survival by itself, even though it inhibited NRF2 signaling (known to promote GPX4 and HO-1 transcription)." (PMID 36899869, 2023). "Although this mechanism has not been directly validated in colorectal cancer (CRC), our findings suggest that HDAC3 may similarly regulate NRF2 expression at the epigenetic level in CRC cells, thereby modulating downstream targets such as GPX4 and contributing to ferroptosis resistance." (PMID 40947430, 2025).
hepatocellular carcinoma (110 papers, 2008 to 2026). A malignant tumor that arises from hepatocytes. "Among these candidates, only miR-214-3p has been mechanistically linked to GPX4 suppression in hepatocellular carcinoma via direct 3′UTR binding." (PMID 40746894, 2025). "PPI inhibits hepatocellular carcinoma (HCC) growth by inducing ferroptosis through the modulation of the Nrf2/HO-1/GPX4 antioxidant axis and causing mitochondrial dysfunction, with effects comparable to those of sorafenib." (PMID 39315094, 2024). "Corroborating this possibility, generated LRP8 KO breast and hepatocellular carcinoma cell lines presented reduced GPX4 levels, with concomitant reduction of Se levels that caused disruption in the GPX4 translation process." (PMID 36358931, 2022). "A study found that the release of miR-6805 from its target genes, apoptosis-inducing factor mitochondria-associated 2 (AIFM2) and GPX4, inhibited ferroptosis and promoted tumor development in hepatocellular carcinoma (HCC)." (PMID 40403492, 2025). "Plumbagin, a natural product DUB inhibitor, uniquely induces glutathione peroxidase 4 (GPX4) ubiquitination and degradation in hepatocellular carcinoma cells via selective USP31 inhibition." (PMID 40918504, 2025). "Immunogenic cell death signaling can also result in greater MDSC recruitment to the tumor microenvironment, as has been demonstrated in a GPX4-suppressed murine model of hepatocellular carcinoma." (PMID 40001204, 2025). "Recent studies have found that PPI significantly inhibits the proliferation, invasion, and metastasis of hepatocellular carcinoma cells by regulating the Nrf2/HO-1/GPX4 axis and inducing ferroptosis and mitochondrial dysfunction." (PMID 40386780, 2025). "This drives hepatocellular proliferation and invasion and confers ferroptosis resistance through up-regulation of c-Myc, Cyclin D1 and glutathione peroxidase 4 (GPX4), fueling the malignant progression of hepatocellular carcinoma." (PMID 41301681, 2025). "TGF-β1 (transforming growth factor β1) can increase hepatoma cell sensitivity to GPX4 inhibitors by suppressing System xc-, which will benefit GPX4-targeted therapy for hepatoma cells." (PMID 40969276, 2025). "Polyphyllin I suppressed hepatocellular carcinoma progression by triggering ferroptosis through mitochondrial dysfunction through the Nrf2/HMOX1/GPX4 axis." (PMID 40137309, 2025). "Elevated 27HC levels in hepatocellular carcinoma cells upregulate glutathione peroxidase 4 (GPX4), leading to ferroptosis resistance and promoting cancer proliferation." (PMID 40270603, 2025). "Remarkably, increasing evidence also points toward GPX4 protein degradation as a means to incite cancer cell ferroptosis and apoptosis in hepatocellular carcinoma and breast cancer cells." (PMID 39090114, 2024). "As an overexpressed circRNA in hepatocellular carcinoma tissues and cells, circIL4R knockdown decreases proliferation and increases ferroptosis via the circIL4R/miR-541-3p/GPX4." (PMID 38778030, 2024). "NeuroD1 promotes resistance to ferroptosis in hepatocellular carcinoma (HCC) by upregulating GPX4, enhancing cell survival and tumorigenic potential, highlighting it as a potential target for antitumor therapy." (PMID 39315094, 2024). "Research has also shown that targeting exosomes from DHODH and GPX4 enhances sorafenib-induced ferritic anaemia, thereby increasing the sensitivity of hepatocellular carcinoma (HCC) cells to sorafenib." (PMID 38509409, 2024). "The interaction between creatine kinase B (CKB) and GPX4 facilitated the phosphorylation of GPX4 at S104, mitigated autophagic degradation of GPX4, and suppressed ferroptosis in hepatocellular carcinoma." (PMID 38844964, 2024).